PARD6B (par-6 family cell polarity regulator beta)
Description:
Adapter protein involved in asymmetrical cell division and cell polarization processes. Probably involved in formation of epithelial tight junctions. Association with PARD3 may prevent the interaction of PARD3 with F11R/JAM1, thereby preventing tight junction assembly. The PARD6-PARD3 complex links GTP-bound Rho small GTPases to atypical protein kinase C proteins.
Synonyms: PAR-6B; PAR6B
Tractability: Antibody: its Gene Ontology location is reachable by antibodies, with high confidence; UniProt places it where antibodies can reach, with medium confidence. PROTAC: ubiquitination databases record sites on it; its protein half-life has been measured.
Gene: Protein-coding gene on chromosome 20 (50,731,382 to 50,756,795, forward strand). Ensembl gene ENSG00000124171.
Subcellular location: Cytoplasm; Cell membrane; Cell junction, tight junction
Subcellular location (Human Protein Atlas): Cell Junctions; Cytosol; Plasma membrane
Pathways (Reactome):
Cell-Cell communication: Tight junction interactions
Signal Transduction: RHOV GTPase cycle
Gene Ontology:
Molecular function: protein binding
Biological process: protein-containing complex assembly; axonogenesis; cell-cell junction assembly; centrosome cycle; establishment or maintenance of cell polarity; regulation of cell migration; regulation of cellular localization
Cellular component: bicellular tight junction; cytosol; extracellular exosome; plasma membrane; apical plasma membrane; cell cortex; nucleus; tight junction; apical part of cell; cytoplasm; protein-containing complex
Genetic constraint (gnomAD): Loss-of-function variants: 2 observed, 6.87 expected, observed/expected ratio (o/e) 0.29, 90% interval 0.12 to 0.92. That is too few expected variants to judge how well the gene tolerates losing a copy. Missense variants: 394 observed, 469.73 expected, observed/expected ratio (o/e) 0.84, 90% interval 0.77 to 0.91. Synonymous variants: 169 observed, 172.41 expected, observed/expected ratio (o/e) 0.98, 90% interval 0.86 to 1.11.
Homologues: Orthologues: chimpanzee PARD6B (100% identical), macaque PARD6B (98% identical), dog PARD6B (98% identical), pig PARD6B (97% identical), guinea pig PARD6B (91% identical), mouse Pard6b (91% identical), rabbit PARD6B (91% identical), rat Pard6b (91% identical), tropical clawed frog pard6b (76% identical), zebrafish pard6b (66% identical), Drosophila melanogaster par-6 (46% identical), Caenorhabditis elegans par-6 (41% identical). Paralogues in human: PARD6G (56% identical), PARD6A (48% identical).
Diseases named in the same sentence as PARD6B in open-access papers:
PARD6B is named in the same sentence as 13 diseases in open-access papers, as found by Europe PMC text mining. Sharing a sentence is not in itself a finding about the gene and the disease. The quoted sentences say what the papers report.
breast carcinoma (4 papers, 2013 to 2020). "Although PARD6B is generally considered to be an oncogene, it has also been linked to suppression of cell proliferation in breast cancer, indicating that the role of this gene may be complex." (PMID 32605588, 2020). "PARD6B has been shown to be amplified in breast cancer; however, in a comparison of BC subtypes, the expression of this protein was specifically proposed to be upregulated in the luminal type compared to basal-like and Her2-enriched tumors." (PMID 32605588, 2020). "PARD6B locus resides in a chromosomal region that is frequently amplified and overexpressed in breast cancer." (PMID 26697513, 2015). "Thus, the genetic and functional evidence suggest a gain-of function i.e. oncogenic mode of activity for PARD6B in breast cancer." (PMID 26697513, 2015). "PARD6B overexpression promotes the activation of MAPK and cell proliferation in breast cancer." (PMID 33318294, 2020).
breast tumors (1 paper, 2025). "In contrast, about one-third of breast tumors show CP gene amplification, including SCRIB (14.7%), LLGL2 (7%), PRKCI (protein kinase C, iota) (5%), PARD6B (partitioning defective 6 homolog beta) (4.9%), DLG1 (3.92%), and DLG2 (discs large homolog 2) (3.92%)." (PMID 40057606, 2025).
dilated cardiomyopathy (1 paper, 2019). Cardiomyopathy which is characterized by dilation and contractile dysfunction of the left and right ventricles. "Of note, several iPTGs, such as ACTA2, FHL2, PARD6B, and SLC30A1, may be linked to iASPP-related phenotypes such as sudden cardiac death and dilated cardiomyopathy." (PMID 31395738, 2019).
E. coli infection (1 paper, 2020). "Six genes (CLDN20, PARD6B, CD151, CDH11, CLDN2 and F11R) related to the GO biological process “Cell junction organization” were upregulated by E. coli infection, whereas these genes were not induced by EPS." (PMID 32234079, 2020).
cancer (8 papers, 2009 to 2025). A tumor composed of atypical neoplastic, often pleomorphic cells that invade other tissues. "Again, the FLNA editing state affected the expression of proliferation-, cancer-, and stress response–associated genes (Junb, Jun, Pard6b, Atf3, Hspa1a and -b, Cyp2c55, and Abcb1a)." (PMID 40471139, 2025). "Of these PARD6B, BCAS4, and KCNG1 are expressed greater than two-fold higher in cancer samples with the amplification relative to normal." (PMID 19419571, 2009). "Moreover, cancer cell–derived FST and PARD6B were positively correlated with CD31+ CD73mid endothelial cell (CD31) density, indicating that these genes modulate endothelial cell activity and subsequently angiogenesis." (PMID 33917869, 2021).
tumor (2 papers, 2019 to 2020). "Meanwhile, MIRLET7C could also inhibit the expression of PARD6B to cause inhibition of the proliferation of tumor cells." (PMID 31126066, 2019). "PARD6B expression is critical for TJ assembly, and decreased expression of this gene has been proposed to result in epithelial cell changes and tumor metastatic behavior." (PMID 32605588, 2020). "TF CEBPB can upregulate target gene PARD6B, whose expression is increased to promote MAPK signaling pathway for tumor cell proliferation." (PMID 31126066, 2019). "Some genes in this module were connected by processes proposed to be involved in tumor progression, such as DOC2A, CGN (Cingulin), PARD6B, NEDD4L, and SYT9 which belonged to the KEGG pathway, tight junction (TJ) (hsa04530), and GEO term, cell junctions (GO:0030054)." (PMID 32605588, 2020).
PARD6B also shares sentences with these, for which no sentence is quoted: adenoma (1 paper); cyst (1); gastrointestinal disease (1); infection (1); lung carcinoma (1); ovarian carcinoma (1); thyroid cancer (1).